BRCA1 (BRCA1 DNA repair associated)
Diseases named in the same sentence as BRCA1 in open-access papers (continued):
Sharing a sentence is not in itself a finding about the gene and the disease.
cancer (continued). "Our study findings did not rule out the possibility of increased risks for these cancers in relatives of BRCA1/2 carriers." (PMID 36861435, 2023). "ART558 sensitivity was observed in an ex vivo culturedtumor organoid derived from a BRCA1 mutantbreast cancer, but not in a BRCA1wt breast cancer organoid cultured under similar conditions." (PMID 37134182, 2023). "Nevertheless, many of these patients result negative to the genetic testing for BRCA1/2 genes PVs and LPVs, even in presence of an evident familiar and/or personal cancer’s background." (PMID 37065479, 2023). "In our evaluated cohort of BRCA1/2 germline PV/LPV carriers, a greater proportion of cancer patients were female (95%) compared to non-cancer patients (64%), and cancer patients were older than non-cancer patients." (PMID 37046302, 2023). "We studied 406 women who were carriers of one of BRCA1 PVs with diagnosed BC or OC, or no cancer diagnosis at the time of recruitment." (PMID 37296919, 2023). "The remaining most frequent mutated cancer driver genes found in early-stage samples (KMT2C, ALK, BRCA2, GRM, ATM, and BRCA1) were not among those found to be the most frequently shared in late-stage samples (MUC16, CSMD3, KNT2C, NF1, LRP1B, SPEN, and TRRAP)." (PMID 37446001, 2023). "Moreover, several BRCA1 and BRCA2 mutant cancer cell lines show limited sensitivity to pharmacologic inhibition of Polθ activity." (PMID 38001070, 2023). "Furthermore, as DNA2 plays a role in DSB repair via HR pathways, the combination of d16 and PARPis can be utilized as a synthetic lethal therapy in BRCA1- and or BRCA2-proficient cancer cells and xenografts." (PMID 37756561, 2023). "Since the discovery of the BRCA1 and BRCA2 genes in 1994 and 1995, the homologous recombination (HR) repair pathway for DNA damage has become a focus area for tumorigenesis and cancer therapy." (PMID 38098088, 2023). "Since ALU sequences are present at high copy numbers within the cell, the presence of R-loops was also examined at promoter sequences around the BRCA1 gene, which has previously been reported to maintain R-loops and whose expression is up-regulated in HPV-positive cancers." (PMID 37611058, 2023). "Blocking RAD52 activity in cancer cells lacking BRCA1/2 proves fatal, underscoring the critical importance of RAD52 in the DNA repair process." (PMID 38136334, 2023). "Differences in the number of cancer types and cancer-affected members among relatives between BRCA1 and BRCA2 carriers, however, were not significant." (PMID 36861435, 2023). "Thus, our prior analysis of EEPD1 in BRCA1-mutant cells and the present results suggest that EEPD1 plays an important role in permitting BRCA1-mutant cancers to survive despite increased oxidative DNA damage including replication fork damage." (PMID 36683914, 2023). "At first, BRCA1 and BRCA2 mutations were identified as biomarkers in HRD, but there still exists some HRD cancer without BRCA1/2 mutations, indicating that some other HR-related genes would potentially affect PARPi sensitivity." (PMID 37476378, 2023). "Latin American countries usually have less infrastructure and resources for genetic testing and treatment of patients with BRCA1/2 than developed countries, and many of the cancer drugs approved in other countries are not available." (PMID 37664050, 2023). "Moreover, the BETi INCB054329 directly represses the transcription of BRCA1 and RAD51 in cancer cells." (PMID 37842243, 2023). "The combined use of PARPIs with histone deacetylase inhibitors (HDIs) can sensitize cancer cells to PARPIs because HDIs block the deacetylation of heatshock protein 90 (HSP90), which leads to the degradation of several proteins such as BRCA1, RAD52, ATR, and CHK1." (PMID 35785170, 2022).
cancer (continued). "Our findings substantially agree with the idea that Wee1 is rapidly recruited at DSBs in response to DNA damage via ATM-γH2AX-MDC1, driving Wee1 to recruit downstream HR repair proteins BRCA1 and RAD51 to DNA damage sites, as well as allowing cancer cells to escape damage and survive." (PMID 36575478, 2022). "The authors analyzed a sample of 133 BRCA1-positive patients who were either diagnosed with primary BC at an age younger than 35 years (early diagnosis, ED) or remained cancer-free until the age of 60 years (late/no diagnosis, LD)." (PMID 35761208, 2022). "The highest numbers of BRCA1/2-defective tumors (class H1a BA/HM) were available for OV (n = 113), BRCA (n = 60), UCEC (n = 14), TGCT (n = 14) and LUSC (n = 10), while less than ten BRCA1/2-defective tumors were at hand for all other cancer types." (PMID 35681079, 2022). "This is particularly the case of scaffold proteins such as BRCA1, BRCA2, and FANC, whose mutations combine cancer predisposition and lack of control of the cell cycle checkpoints (the consequences of their mutations will be discussed in the next chapter)." (PMID 36551628, 2022). "All four patients that harbored BRCA1/2 germline alterations in our cohort confirmed the absence of cancer history in their families." (PMID 35986351, 2022). "MUS81 defects sensitize cells to various genotoxic chemicals, and it was recently shown that inhibition of MUS81 sensitizes HR-proficient cancer cells to the PARP1 inhibitor, olaparib, an agent commonly used to treat cancers with HR defects, such as BRCA1- and BRCA2-defective breast cancers." (PMID 36203968, 2022). "More recently, the effect of PARP inhibitors was also validated in HR-deficient cancers without BRCA1/2 GPVs, suggesting widespread use of PARP inhibitors for cancers caused by GPVs in other HR pathway genes." (PMID 36233090, 2022). "Among patients with HR+/HER2− ABC, overall BRCA1/2mut testing rates were lower for those who had no known family history of BRCA1/2-related cancer compared with those who did have a family history (67% vs. 84%, p = 0.030)." (PMID 36358816, 2022). "Testing rates in the United States and the EU4 were also generally lower among those who were postmenopausal, had no known BRCA1/2-related family history of cancer, and were treated in community medical centers (vs. academic medical centers)." (PMID 36358816, 2022). "Our approach can give a real time observation of BRCA1 and PARP expression in cancer cells, providing an interesting tool for stratifying patients that could benefit from this target therapy." (PMID 35406503, 2022). "Further evaluation of other hub genes (PIK3CAwt, NF1wt, ARID1wt, MYCNOSwt, and MUTYHwt) in BRCA1/2wt, HRP cancer patients as potential biomarkers for Vigil treatment, and possibly indicators of novel added therapeutic management, may be fruitful." (PMID 34785763, 2022). "There is currently no designated specialist service in Ireland for those impacted by a hereditary cancer condition, and often individuals with BRCA1/2 alterations are referred to symptomatic oncology units, regardless of their cancer status." (PMID 35933387, 2022). "Among patients with TNBC, testing rates across all testing groups were not significantly different in patients with and without a known family history of BRCA1/2-related cancer." (PMID 36358816, 2022). "On the other hand, the contribution of rare variants, which are more likely to have large effect sizes and/or direct functional consequences, in modifying cancer risks of BRCA1/2 carriers has not been systematically explored." (PMID 35625955, 2022). "To elucidate whether the elevated S100a9 signaling in cancers could increase MDSC accumulation in mice, we generated doxycycline (DOX) S100a9-inducible B477 cells (Brca1-WT-Dox) and G600 cells (Brca1-MT-Dox)." (PMID 35304461, 2022).
cancer (continued). "The prognostic value of pathogenic mutations in BRCA1/2 and other HRR genes and HRD positivity is not fully understood in cancer patients not treated with PARPi." (PMID 35909902, 2022). "In total, 335 (20.1%) participants carried germline P/LP variants: 167 (10.0%) in BRCA1/2, 122 (7.3%) in BC actionable non-BRCA genes and 47 (2.8%) in candidate genes or other cancer predisposition genes." (PMID 35264596, 2022). "While multimodal screening for HGSOC has not been recommended for women without deleterious germline BRCA1/BRCA2 pathogenic variants, the study findings add evidence to future discussion of potential screening strategies for this serious cancer diagnosis." (PMID 36074460, 2022). "While the genomic and cancer-related actions of BRCA1 have been extensively investigated, not much information exists regarding the cellular and circulating factors involved in regulation of BRCA1 expression and action." (PMID 35432218, 2022). "Moreover, absolute cancer worry scores were almost similar between AYA cancer patients and our BRCA1/2-PV carriers opting for preventive surgery." (PMID 34997316, 2022). "This study highlights the undue burden that individuals with a BRCA1/2 alteration face when trying to navigate a medical system which was not designed with a hereditary cancer population in mind." (PMID 35933387, 2022). "For females without any prior cancer diagnosis who received a BRCA1/2 result from MyCode, mammogram or breast MRI uptake was between 50%–92% and 11%–31% had a risk reducing salpingo-oophorectomy, depending on when the analysis was performed." (PMID 35692820, 2022). "Moreover, we show an enrichment of TDs occurring in cancer driver genes, particularly in the PTEN gene among BRCA1-type BCs." (PMID 35159019, 2022). "The critical functions of BRCA1 and BRCA2 in the repair mechanisms and genome stability have made these genes the target of decades of investigations in the hopes that elucidating their mechanisms can provide new avenues for cancer treatments." (PMID 35626055, 2022). "Two subsequent studies determined the extensive transcriptional characteristics of innate immune genes based on the cGAS–STING pathway in cancer cells lacking BRCA1 or BRCA2." (PMID 36613695, 2022). "The patient without a family history of cancer had several germline mutations: a pathogenic PALB2 mutation, and a VUS in ATM, MLH1, CDK4 and BRCA1." (PMID 36359225, 2022). "More recent studies reported higher prevalence of DCIS incidentally diagnosed during risk reducing mastectomy in BRCA1 and BRCA2 PSV carriers—Kauff and coworkers compared BRCA carriers with age- and race-matched controls without a known cancer predisposition." (PMID 36349178, 2022). "Current clinical studies suggest that PARP inhibitors can play a beneficial role in cancer therapy irrespective of BRCA1/2 or HRD status." (PMID 35873570, 2022). "Out of the 1552 tumors with HRDsum ≥ 42 in the pan-cancer analysis, 9% and 3% had BA and MA deleterious BRCA1/2 alterations (class H1a), 14% and 13% had BA and MA deleterious alterations in other HRR genes (class H1b) and 5% were BRCA1-hypermethylated." (PMID 35681079, 2022). "However, ATF6 inhibition by ceapinA7 still reduced BRCA-1 expression level and increased γH2AX and CHOP expression level also in cancer cells treated by Thapsigargin at low dose (10 nM)." (PMID 35752616, 2022). "This group included 66 (22.7%) with a known PDAC PGV (54 BRCA2, 5 PALB2, 5 ATM, 2 BRCA1) previously identified outside the MDPC on the basis of personal or family history of other cancer diagnoses, but no known PDAC family history." (PMID 35906821, 2022).
cancer (continued). "Further molecular studies on family members were not performed, although multiple cancers of the Li-Fraumeni and BRCA1/BRCA2-spectrum were referred in the maternal family history." (PMID 36003761, 2022). "We compared the carrier frequencies of our candidate variants in different FC groups comprised of cancer cases, regardless of BRCA1 or BRCA2 pathogenic variant status, and cancer-free controls." (PMID 35565380, 2022). "At that moment, 37% of BRCA1-PV and 38% of the BRCA2-PV carriers had high cancer worry." (PMID 34997316, 2022). "A recent systematic review identified ATM, BRCA1, BRCA2, CDKN2A, CHEK2, and PALB2 as the most frequent genes harboring GPV in individuals with PDAC not meeting criteria for any cancer predisposition syndrome with varying degrees of family history." (PMID 35805029, 2022). "Partially due to the technical difficulties in detecting LGR, the profile of BRCA1/2 LGR in Asian cancer patients has not been well elucidated." (PMID 36147908, 2022). "In HGSOC cells with mutant BRCA1/2 or other defective HR genes, the inhibition of PARP forces cancer cells to rely on error-prone repair DNA pathways or otherwise unrepaired damage persist into mitosis, leading to the rapid accumulation of mutations, genomic instability, and eventual cell death." (PMID 36159999, 2022). "Since BRCA1 carriers usually have a higher-grade disease, and more frequently hormone-negative, diagnosing DCIS earlier would be extremely important to try to prevent these carcinomas evolving into an invasive disease." (PMID 36349178, 2022). "Overexpressed Rad51, BRCA1, and MDC1 contribute to genomic integrity and chemoresistance in cancer." (PMID 34025420, 2021). "Up to 45% of cancer patients with an HRD tumor according to CHORD do not have an event in BRCA1 or BRCA2." (PMID 34067105, 2021). "Thus, the normal functions of ATM and BRCA1 are required for preventing malignant transformation, and defects in ATM and BRCA1 genes are observed in human cancers." (PMID 34068585, 2021). "We observed that BRCA1/2 gene alterations were mutually exclusive with amplification of all the oncogenes examined in the breast (CCND1, CCNE1 and CDC6) and ovarian (CCND1, CCNE1 and BRAF) cancer cohorts." (PMID 34389725, 2021). "The concept was further supported by finding that 57.5% of BRCA1 positive cases actually did not meet family cancer history criteria to qualify for BRCA1/2 testing." (PMID 33468216, 2021). "Consistent with the BRCA1 gene, NBR2 expression is usually down-regulated in cancer." (PMID 34926299, 2021). "Olaparib is a clinically used PARP1-i chemotherapeutic agent that is especially effective for treatments of BRCA1 or BRCA2 negative cancers, such as ovarian and breast cancer types." (PMID 33926008, 2021). "However, Olaparib induced cytostatic effects only against the BRCA1-null UWB1.289 and less against OVCAR-3 cancer cells at the tested drug concentrations." (PMID 34440232, 2021). "Multiple studies have demonstrated an overlap between cancer outcomes and BRCA1/BRCA2 carriers despite the lack of homology between these genes." (PMID 34066014, 2021). "Regarding BRCA1/2 mutation carriers who have not undergone RRBSO, HRT does not seem to have a relevant impact on cancer risk." (PMID 33885953, 2021). "In addition, these compounds promoted a more appreciable elevation of the PARP2 mRNA transcription in the BRCA1-null UWB1.289 than BRCA1 wild-type, UWB1.289 + BRCA1 cancer cells." (PMID 34440232, 2021). "Since cyclin E1/CDK2 protects cells from DNA damage and cyclin E1 is elevated in BRCA1 mutant cancers, we hypothesized that CDK2 inhibition would sensitize these cancers to PARP inhibition." (PMID 34465787, 2021). "BRCA1 and BRCA2 cancer cell lines also demonstrated more limited sensitivity to quinacrine." (PMID 33784323, 2021).
cancer (continued). "A similar enrichment for signature 3 was found for PALB2 and RAD51C mutations or epigenetic silencing of the BRCA1 or RAD51C promoter, but not for inactivation of other cancer-associated genes, such as CHEK2 and ATM." (PMID 33670893, 2021). "Our results suggest that hypermethylation of BRCA1 promoter is correlated with a better survival and that conversion of methylation status is a consequence of therapy‐induced selection rather than cancer evolution." (PMID 34601813, 2021). "Surprisingly, BRCA1, RAD51, or RAD51C depletion, unlike BRCA2 depletion, cannot lead to synthetic lethality upon concomitant loss of MUS81 in cancer cells." (PMID 33791310, 2021). "Interestingly, not all cancers arising in BRCA1/2 mutation carriers are characterized by somatic inactivation of the remaining BRCA1/2 allele; therefore, it is advisable to supplement BRCA1/2 germ-line testing with the BRCA1/2 loss-of-heterozygosity (LOH) analysis of the tumor tissue." (PMID 34681592, 2021). "Cancer cell lines lacking BRCA1 or BRCA2 functions demonstrated selective sensitivity to quinacrine, mitoxantrone, and doxorubicin." (PMID 33784323, 2021). "Variant carriers in BRCA1 and BRCA2 pathogenic variant negative OC families were also more frequent when compared to cancer-free FC females by including the OC discovery family in our analysis (P = 0.02, Fisher’s exact)." (PMID 34861889, 2021). "Our bioinformation analysis data shows that ZGRF1 expression also positively correlates with the mRNA levels of BRCA1 and EXO1, which are well known for PARPi targets, and higher expression of ZGRF1 predicts poor prognosis of patients in several types of cancer." (PMID 34552057, 2021). "As in BRCA1/2 mutation carriers, the lack of both PALB2 alleles causes the activation of the NHEJ with a consequent genomic instability and cancer cell death." (PMID 33800556, 2021). "The overall survival rate of patients with BRCA-positive cancers was significantly better, with that of BRCA1/2-positive groups without LOH being as low as that of BRCA-negative groups." (PMID 32862296, 2021). "Little is known about genotypic BRCA1 and BRCA2 features that might be related to earlier onset of cancer." (PMID 34356116, 2021). "Our results show that somatic mutations of BRCA1/2 genes were associated with higher TMB, neoantigen loads, and hypermutator phenotypes even in of non-germline BRCA-associated cancer types, including UCEC, STAD, and COADREAD." (PMID 34095878, 2021). "We identified 99 unique FANCI variants (VAF < 1%) in 516 AUS HGSC BRCA1 and BRCA2 pathogenic variant negative cases and 4878 AUS cancer-free controls from available WES data." (PMID 34861889, 2021). "There was an increased carrier frequency of FANCI c.1813C>T in BRCA1 and BRCA2 pathogenic variant negative OC families, when including the discovery family, compared to cancer-free females (3/23, 13%; OR = 5.8; 95%CI = 1.7–19; P = 0.005)." (PMID 34861889, 2021). "The recency of the COVID-19 pandemic in the US has focused research on the general population and its mental health, while very little, to our knowledge, has been implemented among cancer patients or survivors, and none regarding BRCA1/2-positive women." (PMID 34969949, 2021). "Taken together, cancers with ATM aberrations may rarely respond to PARPis, and the response is, in general, more limited compared with the activity in BRCA1/2 tumors." (PMID 33233320, 2020). "Such a remarkable shift indicates that in cancer cells, BRCA1 fails to cooperate with other conserved collaborators to control the transcriptional process." (PMID 32615918, 2020). "Although there was no reported family history of HBOC-associated cancers, she met National Comprehensive Cancer Network (NCCN) guidelines for BRCA1/2 testing." (PMID 32884827, 2020). "Though governmental cancer care insurance covers for BRCA1 and BRCA2 testing, it does not cover the major part of the reconstruction surgery." (PMID 32733560, 2020).